OBP2B (odorant binding protein 2B)
Description:
Probably binds and transports small hydrophobic volatile molecules.
Synonyms: OBPIIb; hOBPIIb; LCN14
Tractability: Antibody: UniProt places it where antibodies can reach, with high confidence; UniProt predicts a signal peptide or a membrane-spanning region; its Gene Ontology location is reachable by antibodies, with medium confidence.
Gene: Protein-coding gene on chromosome 9 (133,205,277 to 133,209,250, reverse strand). Ensembl gene ENSG00000171102.
Subcellular location: Secreted
Gene Ontology:
Molecular function: odorant binding; small molecule binding
Biological process: chemosensory behavior; sensory perception of smell
Cellular component: extracellular region
Genetic constraint (gnomAD): Loss-of-function variants: 9 observed, 18.53 expected, observed/expected ratio (o/e) 0.49, 90% interval 0.29 to 0.85. The upper end of that interval is the gene's LOEUF score, 0.85, which puts it in group 3 of 6, group 1 being the genes least tolerant of losing a copy. Missense variants: 149 observed, 206.19 expected, observed/expected ratio (o/e) 0.72, 90% interval 0.63 to 0.83. Synonymous variants: 71 observed, 83.53 expected, observed/expected ratio (o/e) 0.85, 90% interval 0.7 to 1.04.
Homologues: Orthologues: chimpanzee OBP2B (77% identical), rat Obp2b (48% identical), mouse Obp2b (48% identical), mouse Obp2a (42% identical), rat Lcn4l2 (40% identical), rat Obp2a (39% identical), rat Lcn4 (37% identical), mouse Lcn4 (36% identical), rat Obp2bl1 (36% identical), rat AABR07051244.1 (26% identical). Paralogues in human: OBP2A (90% identical), LCN1 (46% identical), LCN15 (24% identical), PTGDS (22% identical), LCN9 (20% identical), LCN10 (19% identical), PAEP (19% identical), LCN6 (19% identical), LCN2 (18% identical), LCN12 (16% identical), LCNL1 (15% identical), LCN8 (11% identical).
Diseases named in the same sentence as OBP2B in open-access papers:
OBP2B is named in the same sentence as 7 diseases in open-access papers, as found by Europe PMC text mining. Sharing a sentence is not in itself a finding about the gene and the disease. The quoted sentences say what the papers report.
meningitis (1 paper, 2022). A disorder characterized by acute inflammation of the meninges of the brain and/or spinal cord. "Among the proteins with the lowest FC in the saliva of piglets with meningitis, OBP2B and HBB might be the most relevant." (PMID 36430174, 2022).
infection (1 paper, 2023). The state of being infected such as from the introduction of a foreign agent such as serum, vaccine, antigenic substance or organism. "We also found 12 genes associated with infection at six loci, including four infection-specific genes (TCF19, ABO, OBP2B, and TLE1)." (PMID 37886583, 2023).
OBP2B also shares sentences with these, for which no sentence is quoted: gastric cancer (2 papers); diabetes (1); Obesity (1); Sepsis (1); tumor (1).